IL13 (interleukin 13)
Diseases named in the same sentence as IL13 in open-access papers (continued):
Sharing a sentence is not in itself a finding about the gene and the disease.
atherosclerosis (continued). "ILC2-derived cytokines (IL-5 and IL-13) are therefore vital components controlling the progression of atherosclerosis, particularly IL-13 which may alter macrophage phenotype, and its absence leads to larger and potentially more vulnerable plaques." (PMID 28589929, 2017). "Thus, IL-13 protects from atherosclerosis and promotes a favourable plaque morphology, in part through the induction of alternatively activated macrophages." (PMID 23027612, 2012). "Therefore, we characterized the role of the Th2 cytokine interleukin (IL)-13 in murine atherosclerosis." (PMID 23027612, 2012). "Importantly, cross-sectional analyses of lesions in the aortic origin revealed significantly accelerated atherosclerosis with almost two times larger lesions in IL-13−/− bone marrow recipients, indicating a protective role of IL-13 in atherogenesis." (PMID 23027612, 2012). "IL-13 therapy may be a potential novel target for preventing and treating atherosclerosis." (PMID 33029103, 2020). "Thus, augmentation of ILC2 and ILC2-derived IL-5 or IL-13 on top of Treg expansion might constitute a potentially attractive double-hit therapy to limit accelerated atherosclerosis." (PMID 28589929, 2017). "The Th2 cytokines IL-4 and IL-13 promote an anti-inflammatory macrophage phenotype through the transcription factor STAT6, and were, thus, proposed as therapies for atherosclerosis." (PMID 36994095, 2023). "We investigated the roles of the cytokines IL-4 and IL-13, the classical activators of STAT6, in the resolution of atherosclerosis inflammation." (PMID 33720008, 2021). "To begin to understand the factors upstream of STAT6 needed for atherosclerosis resolution, we examined the requirements for the canonical activators of STAT6, namely IL-4 and IL-13." (PMID 33720008, 2021). "Recent studies have demonstrated that innate lymphoid cell type-2 derived IL-13 and IL-5 cytokines in PVAT are important to maintain atheroprotective IgM producing B-1 cells in PVAT and attenuate diet induced atherosclerosis." (PMID 28970806, 2017). "Using mice specifically deficient in ILC2, we show that endogenous ILC2 perform a central role in controlling the progression of atherosclerosis and this effect is in part dependent on ILC2-derived IL-5 and IL-13." (PMID 28589929, 2017). "Nevertheless, macrophage content of the same lesions was significantly lower in IL-13-injected mice compared to PBS-injected mice, thereby confirming our initial observation in a different atherosclerosis-prone mouse strain." (PMID 23027612, 2012). "A modest ability of IL-4 to augment macrophage superoxide generation as compared to IL-13 is unlikely to have a major physiological impact that would explain opposing roles in cardiovascular disease such as atherosclerosis, hypertension, or MI." (PMID 37949903, 2023). "In vitro, Mφs stimulated with IL-13 increased the uptake of oxLDL by CD36 upregulation and induced the expression of the lipid exporter (ABCA1), preventing foam cell formation, which is a major driver of atherosclerosis." (PMID 35488301, 2022). "In the present study, we aimed at determining the signals upstream of STAT6 that induce resolution of atherosclerosis and hypothesized that the classical activators of STAT6, IL-4, and/or IL-13 are involved." (PMID 33720008, 2021). "Additionally, increasing IL-10, IL-4, IL-13, and TGF-β and reducing IL-1β, Il-6, TNF-α, CCL3, CCL4, and CCL5 can slow the progression of atherosclerosis." (PMID 32346605, 2020).
atherosclerosis (continued). "While IL-33 exacerbates autoimmune collagen-induced arthritis via mast cell degranulation 22, it also promotes type 2 immune responses with the production of high levels of IL-5 and IL-13 20 and drives M2 macrophage differentiation thus protecting mice from EAE 26 and atherosclerosis." (PMID 25116404, 2014). "Although it has been assumed that IL-13 affects atherosclerosis in the same way as IL-4, no studies are currently available to support this notion." (PMID 23027612, 2012). "Thus, resolution of atherosclerosis was similar in WT and Il4-/-Il13-/- recipients, indicating that IL-4/13 production by cells newly recruited is not essential for resolution of atherosclerosis." (PMID 33720008, 2021).
diabetes (39 papers, 2008 to 2025). "IL-4 circulating levels are decreased in elderly people and low levels of IL-13 are associated with increased mortality risk in diabetes." (PMID 39193712, 2025). "In this epidemiological study, plasma IL-13 was inversely linked with progression from normoglycemia to pre-diabetes, incidence of type 2 diabetes, and initiation of insulin therapy." (PMID 32948777, 2020). "More recently, IL-13, as an inflammatory marker, was found to be associated with the conversion of normoglycemia into type 2 diabetes mellitus and the initiation of insulin therapy." (PMID 31656196, 2019). "Higher EN-RAGE levels were associated with an increased risk of incident pre-diabetes, whereas higher IL13 levels were associated with a decreased risk of pre-diabetes, incident type 2 DM and need for insulin therapy." (PMID 28258520, 2017). "Various inflammatory markers are associated with progression from normoglycemia to pre-diabetes (IL13, EN-RAGE, CRP), T2D (IL13, IL17, CRP) or insulin therapy start (IL13)." (PMID 28258520, 2017). "Furthermore, shifts in TNFa and IP-10 at T4 and sCD40L, IL-9, and IL-13 at T0 were associated with diabetes mellitus progression with impaired glucose tolerance." (PMID 37629267, 2023). "Since vitamin D deficiency upregulates inflammatory mediators (IL-13 and IL-17) in diabetes and diabetic neuropathy, it can be suggested that vitamin D deficiency may be a modifiable risk factor." (PMID 35625788, 2022). "For example, of 26 inflammatory biomarkers evaluated in a longitudinal analysis of ~1000 subjects from the Rotterdam Study, plasma IL-13 levels were inversely associated with progression from normoglycemia to pre-diabetes, incident T2DM, and initiation of insulin therapy." (PMID 30755607, 2019). "We hypothesized that, in diabetes mellitus, rs1881457C could reduce the IL-13 level and consequently increase the risk of CAD." (PMID 29670225, 2018). "Finally, IL-13 level, adjusted to HbA1C, turned out to be a risk factor for albuminuria with preserved renal function.The elevated production of IL-13 in the kidney was described recently in a model of streptozotocin-induced diabetes." (PMID 32961903, 2020). "NaB ameliorated diabetes-related sarcopenia through the ILC2s/IL-13/STAT3 pathway, and dietary NaB supplementation promoted the expressions of myosin heavy chain I (MyHCI) and MyHCIIα to promote oxidative fiber growth in skeletal muscle." (PMID 40005024, 2025). "Corresponding to our global correlation analyses, APMB patients with diabetes had lower levels of IL-13 and trended toward decreased CCL4 as compared to those who did not." (PMID 39966757, 2025). "Vaccine treatment was associated with significantly higher levels of the regulatory cytokine IL13 in mice with progressive compared with the acute onset diabetes (Wilch’s t test, p = 0.03)." (PMID 38781241, 2024). "The high-glucose environment of diabetes significantly increases the cytokines, such as interleukin 4(IL-4), interleukin 5(IL-5), interleukin 6(IL-6), interleukin 13(IL-13), and tumor necrosis factorα (TNF-α)." (PMID 35669482, 2022). "During the co-occurrence of opisthorchiasis and diabetes, Il-6, Il-12 and Il-13 were dominantly increased." (PMID 29953446, 2018). "Among them, EN-RAGE is a novel inflammatory marker for pre-diabetes, IL17 for incident type 2 DM and IL13 for pre-diabetes, incident type 2 DM and insulin therapy start." (PMID 28258520, 2017). "In age and sex adjusted Cox models, IL13 (HR = 0.78), EN-RAGE (1.30), CFH (1.24), IL18 (1.22) and CRP (1.32) were associated with incident pre-diabetes." (PMID 28258520, 2017). "In multivariate models, IL13 (0.77), EN-RAGE (1.23) and CRP (1.26) remained associated with pre-diabetes." (PMID 28258520, 2017). "Among them, EN-RAGE is a novel inflammatory marker for pre-diabetes, IL17 for incident T2D and IL13 for pre-diabetes, incident T2D and insulin therapy start." (PMID 28258520, 2017).
diabetes (continued). "In age and sex adjusted model, EN-RAGE, IL13, CFH, IL18 and CRP were associated with incident pre-diabetes." (PMID 28258520, 2017). "In multivariate models, IL13 (HR = 0.77), EN-RAGE (HR = 1.23) and CRP (HR = 1.26) remained associated with incident pre-diabetes." (PMID 28258520, 2017). "For example, a systemic administration of recombinant IL-13 prevents the onset of diabetes in NOD mice." (PMID 23390544, 2013). "In this study, we have identified a group of APMB-specific analytes (IL-10, CXCL1, IL-12p40, IL-13, CCL22, CCL4, IL-17A, and TGFα) that correlates with several clinical phenotypes associated with more severe SAB (diabetes, dialysis dependence, metastatic infection, and cardiac vegetation)." (PMID 39966757, 2025). "In the periodontally healthy sites, the concentrations of IL-4, IL-5, IL-7, and IL-13 were decreased in the diabetes group compared to those in the control group; TGF-β concentrations were also decreased in the control group versus those in the rest of the groups (p < 0.05)." (PMID 37835794, 2023). "IL-13 plays a key role in regulating glucose homeostasis by modulating gluconeogenesis and may be a useful therapeutic target for treatment of diabetes and metabolic syndrome." (PMID 28969688, 2017). "Notably, we found a trend for increased expression of the Il13 gene in a subset of donor hearts with a history of diabetes mellitus." (PMID 28528324, 2017). "The interaction between diabetes and IL13 levels is complex and deserves further specific studies." (PMID 26064774, 2015). "We found EN-RAGE as a novel inflammatory marker for pre-diabetes and for CHD, IL17 for incident T2D and IL13 for pre-diabetes, incident T2D and insulin therapy." (PMID 32367290, 2020). "Among inflammatory markers, we found EN-RAGE to be a novel inflammatory marker for pre-diabetes, IL17 for incident T2D and IL13 for pre-diabetes, incident T2D and insulin therapy start." (PMID 29064009, 2017). "Additional models controlling for gender, pulmonary source of infection, and diabetes were built for EGF, VEGF, IL4, IL5, and IL13." (PMID 26064774, 2015). "In those individuals with type 1 and type 2 diabetes who harbored detectable vaccine‐specific T cells, they displayed an unfocused, tolerogenic phenotype characterized by increased expression of IL‐10 and IL‐13 compared with people without diabetes." (PMID 41367201, 2025). "Nevertheless, it is known that exogenous administration of IL-13 or IL-4 reduces the incidence and delays the onset of diabetes in the NOD mouse model of type 1 diabetes and that IL-4 and IL-13 each exert direct pro-survival effects in human pancreatic islet cells." (PMID 30338340, 2019). "In those diabetes participants where S‐specific T cells were detected, the response was unfocused, with the expected expression of IFNγ, TNF, and IL‐2, alongside a significant increase in the expression of the Th2 cytokine IL‐13 in S‐specific CD4+ and CD8+ T cells from both diabetes groups." (PMID 41367201, 2025). "In people without diabetes SRA1 expression was associated with CCL3 (r = 0.298, p = 0.036), CCL8 (r = 0.344, p = 0.021), CXCL11 (r = 0.400, p = 0.003), TNF-α (r = 0.317, p = 0.030), TGF-β (r = 0.514, p < 0.0001), IL13 (r = 0.310, p = 0.028), and IL18 (r = 0.547, p < 0.0001)." (PMID 34685582, 2021).
emphysema (39 papers, 2006 to 2025). "These latter studies also indicated a critical role for DUOX1 in production of IL-13 during allergic inflammation, but Il13 induction in the context of PPE-induced emphysema was unaltered in Duox1-deficient mice." (PMID 33301419, 2021). "ILC2‐deficient mice were protected from CS‐induced emphysema, but had increased collagen deposition, and IL‐33 and IL‐13 expression." (PMID 30260499, 2019). "We observed increases in CS-exposed aged mice for Rorγt, the master transcription factor of Th17 cells, and for IL-13, a Th2-associated cytokine also involved in emphysema development in a transgenic mouse model." (PMID 26284585, 2016). "MT1-MMP expression is upregulated in alveolar macrophages of smokers, and IL-13–driven emphysema in transgenic mouse models is associated with MT1-MMP upregulation." (PMID 26091717, 2015). "Furthermore, TGF-β1, for example, is known to play an major role in the differentiation of fibroblasts into myofibroblasts and eosinophil-derived IL-13 is closely associated with emphysema." (PMID 34743726, 2021). "This demonstrates that IL-13 causes emphysema through MMPs and cathepsins which might be part of the pathological alterations causing COPD." (PMID 28076408, 2017). "In experimental studies, the overexpression of IL-13 in the adult murine lung caused emphysema." (PMID 23267696, 2012). "Pathologically, IL-4– and IL-13–mediated processes align with hallmark COPD features such as airway barrier disruption, mucus plug formation, fibrotic remodeling, and emphysema." (PMID 41024111, 2025). "Meanwhile, IL-13 produced by Eos was able to induce matrix metalloproteinase-12 secretion by rat alveolar macrophages, which in turn induced emphysema." (PMID 40337271, 2025). "Type 2 cytokines (e.g., IL-4 and IL-13) promote mucus hypersecretion, airway remodeling, and emphysema by enhancing mucin synthesis, airway mucosal permeability, fibrin deposition, and protease production." (PMID 40589761, 2025). "Earlier studies further support this, showing that IL-13 overexpression leads to a phenotype characterized by significant emphysema and lung enlargement." (PMID 40004650, 2025). "IL-13 is capable of promoting M2 polarisation and MMP-12 production in macrophages and in mice, where over-expression of IL-13 was found to induce emphysema that was dependent on MMPs, with eosinophils identified to be a rich source of IL-13." (PMID 38614991, 2024). "Chronic lung inflammation induced by IL-13 promotes emphysema via the stimulation of alveolar macrophages to release matrix metalloproteinase (MMP)-12 and induces airway space enlargement." (PMID 35740358, 2022). "In this study, CCL-17 was significantly decreased in the emphysema group, whereas IL-13 and IL-4 were elevated." (PMID 36248880, 2022). "As N. brasiliensis infection eventually results in emphysema that resemble features of COPD, our data thus suggest a complex role for IL-13 in the development of emphysema." (PMID 34127548, 2021). "It has been suggested that eosinophil-derived IL-13 enhances emphysema by stimulating macrophages to secrete MMP-12." (PMID 34950055, 2021). "CS‐exposed Rorafl/flIl7rCre mice were protected from emphysema, but had increased IL‐33/IL‐13 expression and collagen deposition compared to WT CS‐exposed mice." (PMID 30260499, 2019). "Studies in murine models showed that over expression of IL13 produces cathepsin and matrix metalloproteinase dependent emphysema, mucus metaplasia and inflammation." (PMID 24587150, 2014). "IL-13 has been previously shown to induce mucous metaplasia and chemokine expression in animal models of allergic airway inflammation and emphysema." (PMID 17868461, 2007). "Studies in transgenic mice have shown that if IL13 is over expressed, it results in cathepsin and matrix metalloproteinase dependent emphysema with mucus metaplasia." (PMID 17054776, 2006).
emphysema (continued). "Eosinophil-derived cytokines (such as IL-13) and chemokines attract other inflammatory cells, such as macrophages and neutrophils, and the enzymes and reactive species produced by these cells exacerbate emphysema symptoms and drive disease progression." (PMID 40244222, 2025). "Synergistically, IL-4 and IL-13 drive M2 macrophage polarization, B cell class-switching, IgE production, mast cell degranulation, epithelial barrier dysfunction, airway hyperresponsiveness, fibrotic remodeling, and emphysema." (PMID 41024111, 2025). "The bronchoalveolar lavage (BAL) interleukin 13 (IL‐13), IL‐4, and IL‐5 levels in the overlap model were higher than in the pulmonary emphysema model and lower than in the type 2 airway inflammation model, but IL‐33 level in the lung was higher than in other models." (PMID 38652015, 2024). "The reduction of CCL-17 suggests that the reduction of M2 macrophages in emphysema is mainly dominated by the M2a subtype, and the reduction of the M2a subtype in turn stimulates the increase of IL-13 and IL-4, and also leads to a decrease in anti-inflammatory capacity." (PMID 36248880, 2022). "Nevertheless, both IFN-γ and IL-13 inflammation can induce emphysema." (PMID 33731130, 2021). "Intriguing recent studies demonstrated that IL-13 induction within the alveolar epithelium impairs self-renewal and differentiation properties of alveolar type 2 cells, which is likely relevant to alveolar remodeling and emphysema development." (PMID 33301419, 2021). "Interestingly, cathepsin H has been shown to be upregulated in an IL-13 induced emphysema murine model." (PMID 24729918, 2014). "Additionally, conditional lung-specific IL-13 expression with IFN-γ overproduction in the lungs induces emphysema in adult mice." (PMID 23382928, 2013). "Previously, we showed that constitutive overproduction of mature IL-18 protein in the lungs of B6 background transgenic mice resulted in the increased production of IFN-γ IL-5, and IL-13, and severe emphysema accompanied by pulmonary inflammation, especially by CD8+ T cells." (PMID 23382928, 2013). "Overexpression of prototypical M1-inducer IFNγ may be able to induce emphysema, but so does overexpression of prototypical M2 induced IL-13." (PMID 23533311, 2013). "In mice IL13 induced emphysema is characterised by excessive pulmonary mucus production, so further studies looking for the prevalence of this polymorphism in the subgroup of COPD patients with chronic bronchitis might be worthwhile." (PMID 17054776, 2006). "Thus, we believe that localized production of IL-18 in the lungs may play an important role in the development of pulmonary inflammation and emphysema via IL-13 production in mice as well as COPD patients." (PMID 23382928, 2013). "Compared to the emphysema model (ELA), the ACO group was superior in expressing of IL-1β, IL-4, IL-5, IL-6, IL-13, and IFN-γ." (PMID 37511021, 2023). "Overexpression of CatS was observed in mouse models of experimental emphysema induced by IL-13 or IFN-γ; conversely, CatS inhibition by pharmacological inhibitors reduces significantly the severity of emphysema and inflammation." (PMID 32178437, 2020). "Studies of transgenic mice that overexpress IL-13 and IFN-γ in an inducible- and lung-specific manner develop lung inflammation and emphysema due, in part, to increased lung levels of cysteine proteinases including cathepsin S." (PMID 27994288, 2016). "Recently, it has also been reported that overexpression of IL-18 induced emphysema via IFN-γ and IL-17A, and induced mucus metaplasia via IL-13." (PMID 23331548, 2013). "At day 3 post infection, treatment with IL-6, IL-13, and IFN-γ provoked mild PE and severe emphysema that were accompanied by pulmonary dysfunction in EV71-infected, but not herpes simplex virus-1 (HSV-1)-infected control mice." (PMID 22054060, 2011).